ZNF625 (zinc finger protein 625)
Description:
May be involved in transcriptional regulation.
Tractability: PROTAC: ubiquitination databases record sites on it.
Gene: Protein-coding gene on chromosome 19 (12,142,090 to 12,156,734, reverse strand). Ensembl gene ENSG00000257591.
Subcellular location: Nucleus
Subcellular location (Human Protein Atlas): Mitochondria; Nucleoplasm
Pathways (Reactome):
Gene expression (Transcription): Generic Transcription Pathway
Gene Ontology:
Molecular function: protein binding; DNA-binding transcription factor activity, RNA polymerase II-specific; RNA polymerase II transcription regulatory region sequence-specific DNA binding
Biological process: regulation of transcription by RNA polymerase II
Cellular component: nucleus
Genetic constraint (gnomAD): Loss-of-function variants: 8 observed, 9.85 expected, observed/expected ratio (o/e) 0.81, 90% interval 0.47 to 1.46. That is too few expected variants to judge how well the gene tolerates losing a copy. Missense variants: 265 observed, 360.88 expected, observed/expected ratio (o/e) 0.73, 90% interval 0.66 to 0.81. Synonymous variants: 112 observed, 122.87 expected, observed/expected ratio (o/e) 0.91, 90% interval 0.78 to 1.07.
Homologues: Orthologues: chimpanzee ZNF625 (99% identical). Paralogues in human: ZNF136 (64% identical), ZNF627 (63% identical), ZNF670 (52% identical), ZNF527 (43% identical), ZKSCAN7 (42% identical), ZNF287 (42% identical), ZNF426 (42% identical), ZNF852 (42% identical), ZNF17 (41% identical), ZNF333 (39% identical), ZNF34 (39% identical), ZNF214 (39% identical), and 38 more.
Diseases named in the same sentence as ZNF625 in open-access papers:
ZNF625 is named in the same sentence as 2 diseases in open-access papers, as found by Europe PMC text mining. Sharing a sentence is not in itself a finding about the gene and the disease. The quoted sentences say what the papers report.
cancer (2 papers, 2011 to 2023). A tumor composed of atypical neoplastic, often pleomorphic cells that invade other tissues. "The zinc finger protein 625, LON peptidase N terminal domain and ring finger 2, WD repeat domain 17, and syndecan 2 CpG island promoters were methylation in both cancer and laterally spreading tumor non-granular (LST NG)." (PMID 37719843, 2023).
ZNF625 also shares sentences with these, for which no sentence is quoted: tumor (2 papers).